EXOG (exo/endonuclease G)
Description:
Endo/exonuclease with nicking activity towards supercoiled DNA, a preference for single-stranded DNA and 5'-3' exonuclease activity.
Synonyms: ENDOGL1; ENDOGL2; ENGL; ENGL-a; ENGL-b; ENGLA; ENGLB
Tractability: PROTAC: ubiquitination databases record sites on it; its protein half-life has been measured.
Gene: Protein-coding gene on chromosome 3 (38,496,127 to 38,542,161, forward strand). Ensembl gene ENSG00000157036.
Subcellular location: Mitochondrion inner membrane
Subcellular location (Human Protein Atlas): Mitochondria
Pathways (Reactome):
DNA Replication: Strand-asynchronous mitochondrial DNA replication
Gene Ontology:
Molecular function: 5'-3' exonuclease activity; endonuclease activity; protein binding; DNA endonuclease activity; RNA endonuclease activity; hydrolase activity; metal ion binding; nucleic acid binding
Biological process: apoptotic DNA fragmentation
Cellular component: mitochondrial inner membrane; mitochondrion; protein-containing complex; mitochondrial matrix; nucleus
Genetic constraint (gnomAD): Loss-of-function variants: 19 observed, 15.3 expected, observed/expected ratio (o/e) 1.24, 90% interval 0.86 to 1.77. The upper end of that interval is the gene's LOEUF score, 1.77, which puts it in group 6 of 6, group 1 being the genes least tolerant of losing a copy. Missense variants: 354 observed, 359.07 expected, observed/expected ratio (o/e) 0.99, 90% interval 0.9 to 1.08. Synonymous variants: 114 observed, 139.13 expected, observed/expected ratio (o/e) 0.82, 90% interval 0.7 to 0.96.
Homologues: Orthologues: chimpanzee EXOG (99% identical), macaque EXOG (88% identical), pig EXOG (88% identical), dog EXOG (86% identical), guinea pig EXOG (85% identical), mouse Exog (83% identical), rat Exog (77% identical), tropical clawed frog exog (59% identical), Drosophila melanogaster CG14120 (18% identical), Drosophila melanogaster CG33346 (15% identical), Drosophila melanogaster CG3819 (15% identical), Drosophila melanogaster CG6839 (15% identical), and 4 more. Paralogues in human: ENDOG (28% identical).
Diseases named in the same sentence as EXOG in open-access papers:
EXOG is named in the same sentence as 4 diseases in open-access papers, as found by Europe PMC text mining. Sharing a sentence is not in itself a finding about the gene and the disease. The quoted sentences say what the papers report.
depression (1 paper, 2023). "Several unique results were obtained only in early onset depression: alleles of EXOG c.-188T > G (rs9838614) modulated its risk, while the C/C genotype of ENDOG c.-220C > T (rs2997922) had a protective effect." (PMID 37834200, 2023). "Though alleles of EXOG c.-188T > G (rs9838614) modulated the risk of moderate depression only and the T/G genotype of the same SNP increased this risk, the G/G genotype had a protective effect only against severe depression." (PMID 37834200, 2023). "Analysis revealed that the haplotypes of both genes influenced the incidence of depression: TG and GA of EXOG and CC of ENDOG had a protective effect, while TT of EXOG and CT and TT of ENDOG significantly increased the OR of an episode occurrence." (PMID 37834200, 2023). "All SNPs of EXOG and ENDOG modulated the risk of depression, but the strongest effect was observed for rs1065800, while rs9838614 and rs2977998 indicate that they might influence the severity of symptoms, and, to a lesser extent, treatment effectiveness." (PMID 37834200, 2023). "According to the best of our knowledge, this paper is the first to report that SNPs located in genes encoding proteins maintaining mitochondrial genome integrity, i.e., EXOG, POLG and ENDOG, affect the incidence, onset, severity and treatment of depression." (PMID 37834200, 2023).
lung adenocarcinoma (1 paper, 2016). A carcinoma that arises from the lung and is characterized by the presence of malignant glandular epithelial cells. "In cultured lung adenocarcinoma but not in normal lung epithelial cells elevated H2S stimulates mitochondrial DNA repair through sulfhydration of EXOG, which, in turn, promotes mitochondrial DNA repair complex assembly, thereby enhancing mitochondrial DNA repair capacity." (PMID 27808278, 2016). "The interaction between EXOG with APE1, PolG or Lig3, but not between nuclear-specific DNA repair enzymes FEN1 and PolB, was markedly reduced by H2S biosynthesis inhibition in lung adenocarcinoma (but not in normal epithelial cells)." (PMID 27808278, 2016).
viral infection (1 paper, 2025). "The median expression of some genes (CTBP1, LAPTM4B, CFAP45, DSC2, LAMP1, EXOG, RPS21, and SIRPB1) was higher in bacterial compared to viral infection." (PMID 41496780, 2025).
tumour (1 paper, 2020). "The variants in EXOG, RANBP2, RANBP6 and TNFRSF1B were sequenced in the tumour DNA of P1 to assess which allele of the gene was lost." (PMID 32357859, 2020). "Missense variants in four genes, EXOG, RANBP2, RANBP6 and TNFRSF1B, were identified in areas of LOH seen in the tumour from P1." (PMID 32357859, 2020). "The missense variants in EXOG, RANBP6 and TNFRSF1B remained heterozygous in the primary tumour of P1, although with the loss of the second allele at a later stage, this does not necessarily exclude these variants as possible PMP predisposition genes on these data alone." (PMID 32357859, 2020). "Four genes (EXOG, RANBP2, RANBP6 and TNFRSF1B) harboured missense variants that fell in a region of LOH in the tumour from the father only, but none showed somatic loss of the wild type allele in the tumour." (PMID 32357859, 2020).